INS (insulin)
Diseases named in the same sentence as INS in open-access papers (continued):
Sharing a sentence is not in itself a finding about the gene and the disease.
Insulin resistance (continued). "Aging increases the risk of developing T2DM by both impairing insulin secretion and enhancing insulin resistance through obesity and sarcopenia." (PMID 32164656, 2020). "At a placental level, adiponectin causes insulin resistance by activating PPARα and inhibiting insulin receptor substrate 1 phosphorylation, which reduces insulin responsiveness." (PMID 33029393, 2020). "Impaired insulin signaling is associated with the development of insulin resistance, obesity, and hyperglycemia, which are a hallmark of T2D." (PMID 32168855, 2020). "Insufficient insulin secretion and insulin resistance are associated with the pathophysiology of T2DM development." (PMID 32922204, 2020). "In obesity-induced insulin resistance, inflammatory cytokines and free fatty acids (FFAs) released from adipose tissue are involved in insulin sensitivity, and are reportedly caused by abnormal insulin signaling in obese models." (PMID 32260306, 2020). "Work on animal models of AD, T2D, or insulin resistance also points toward an association between insulin signaling and AD-like pathology." (PMID 32265637, 2020). "Obesity is associated with the development of insulin resistance, but only individuals who lack sufficient insulin secretion to match the degree of insulin resistance will develop type 2 diabetes." (PMID 32757152, 2020). "They demonstrated that ADPN deficiency was associated with cerebral insulin resistance and deregulated insulin signaling." (PMID 32188008, 2020). "Researchers have also found that insulin-resistance reduction resulted from TMZ treatment is associated with the alleviated insulin signaling pathway phosphatidylinositol 3-kinase (PI3-K)/Akt." (PMID 33680027, 2020). "As Col24α1 was increased by >10-fold in the muscle of insulin-resistant mice, we further examined its association with diet-induced insulin resistance." (PMID 32785142, 2020). "The main physio-pathological process of T2D is the state of sustained hyperglycemia caused by pancreatic β-cells impaired insulin secretion and/or cell insulin resistance (IR)." (PMID 32726990, 2020). "Insulin resistance is mainly caused by imbalance between increased needs of insulin and β‐cell defect in pregnancy complicated with GDM." (PMID 32537767, 2020). "Insulin Resistance (IR) leads to a loss of response from the peripheral insulin target tissues (mainly the liver, adipose, and muscle tissues) to insulin." (PMID 32927754, 2020). "Its role in insulin deficiency and insulin resistance is implicated via insulin/PI3-kinase/protein kinase B (insulin/PI3K/Akt) signalling pathway." (PMID 32283762, 2020). "Silencing SNX5 in animal models increases blood insulin, decreases insulin excretion, and causes insulin resistance." (PMID 33374212, 2020). "Estrogen deficiency can also induce insulin resistance, decreasing insulin releasing and β-cell apoptosis." (PMID 33092635, 2020). "Obesity is strongly linked to insulin resistance, with excess plasma free fatty acids (FFAs) impairing the ability of insulin to suppress hepatic glucose output and to stimulate glucose uptake by fat and muscle cells." (PMID 31906278, 2020). "Patterns involving prolonged exposure of plasma insulin and failure to return to basal level were implicated in the development of insulin resistance and type 2 diabetes." (PMID 32366255, 2020). "Regulation of insulin secretion is also a key enrichment GO term, and midtrimester maternal insulin resistance is associated with subsequent PE." (PMID 32000849, 2020). "An inverse association of rs1260326 with 2-hydroxybutyrate has been reported in non-gravid populations; 2-hydroxybutyrate is associated with insulin resistance and was reduced after gastric bypass, as weight and insulin resistance decreased." (PMID 32556615, 2020). "Inositol phosphoglycan is an intracellular insulin mediator, which is associated with insulin sensitivity in conditions of insulin resistance, such as T2D." (PMID 32646482, 2020).
Insulin resistance (continued). "Pro-inflammatory M1-macrophages are key factors in generating inflammatory molecules, such as TNFα, IL-1ß and IL-6, that cause insulin resistance both in adipose tissue and other insulin-sensitive tissues." (PMID 32183037, 2020). "We further determined the mechanism underlying hepatic ApoJ deficiency-induced insulin resistance by investigating insulin signaling in insulin-sensitive tissues." (PMID 32332780, 2020). "Reduced hepatic insulin clearance is reportedly associated with insulin resistance and diet-induced obesity in rats and with diabetic conditions in humans." (PMID 32718046, 2020). "Post-transplant diabetes after transplantation (PTDM), often a result of insulin resistance and deficient insulin production, is a serious complication in renal transplant recipients." (PMID 32069900, 2020). "Insulin is used to treat type 2 diabetes, but it causes side effects such as insulin resistance or fatty liver." (PMID 32977701, 2020). "ADAMTS9 is a risk gene for type 2 diabetes development and its over-expression is associated with impaired insulin signaling in peripheral tissues and also with insulin resistance." (PMID 32316129, 2020). "Elevated plasma FFA levels can cause insulin resistance and inflammation in the major insulin target tissues (including skeletal muscle and liver) and represent a key link between obesity, insulin resistance, inflammation, and the development of T2D25." (PMID 32532984, 2020). "Hyperinsulinemia during insulin infusion in humans leads to systemic insulin resistance, while in vitro, high ambient insulin concentrations cause an increase in insulin resistance in isolated adipocytes." (PMID 32819363, 2020). "Genetically higher IGF-1 levels were additionally associated with some components of the metabolic syndrome, the most robust association being with fasting insulin and insulin resistance." (PMID 32548700, 2020). "Variants in AKT2 and PTEN have been associated with type 2 diabetes risk; their presence reduces activity of the insulin signalling pathway, leading to reduced glucose uptake and insulin resistance in insulin-responsive tissues." (PMID 32705315, 2020). "Insulin resistance is the main underlying pathology in T2DM in which cells are unable to respond to insulin effectively and thereby have a suboptimal uptake of glucose." (PMID 32215179, 2020). "Insulin-induced cytokine production in macrophages has also been implicated in the induction of insulin resistance in hepatocytes through ERK1/2 and Inhibitor of κB kinase β (IKKβ) activation." (PMID 32872540, 2020). "PPARα-deficient ob/ob mice with obesity-related insulin resistance develop pancreatic β-cell dysfunction characterized by reduced mean islet surface area and decreased insulin secretion in response to high glucose." (PMID 32708786, 2020). "It has also been reported that hyperuricemia “mediates increased insulin resistance and decreased insulin release”, and studies have shown an association of hyperuricemia with T2DM and a wide range of health outcomes." (PMID 32879892, 2020). "A hallmark of insulin resistance is a reduced ability of a physiological insulin concentration to stimulate muscle glucose uptake." (PMID 33153226, 2020). "When liver, muscle and adipose tissues are less sensitive to insulin, it will cause relative insulin resistance (IR)." (PMID 32756447, 2020). "Insulin resistance is associated with impaired glucose uptake, resulting from defective post-receptor insulin responses, decreased glucose transport, impaired glucose phosphorylation, oxidation and glycogen synthesis in the muscle." (PMID 32977552, 2020). "Since neuronal insulin resistance and hyperinsulinemia are considered as the important risk factors in cognitive impairment as well as AD, several antidiabetic drugs like insulin sensitizers have been currently investigated for the treatment of this disease." (PMID 32138327, 2020).
Insulin resistance (continued). "Despite different causes of the disease (failure in insulin production or insulin resistance), the effect of the disease remains the same: hyperglycaemia." (PMID 32012942, 2020). "Increased accumulation of DAG is inversely correlated with insulin sensitivity and is one of the factors causing the development of insulin resistance in skeletal muscle." (PMID 32466765, 2020). "The most plausible explanation for these effects of A. squamosa is the alleviation of insulin resistance caused by high-fat feeding which increases pancreatic insulin demand." (PMID 33053901, 2020). "When studying insulin resistance one can employ transgenic mice bearing gene deletions or mutations in genes required for insulin action and/or insulin secretion." (PMID 33536868, 2020). "The possible mechanism of insulin resistance includes reduced insulin receptors in fat cells, loss of signal transduction after the binding of normal insulin to normal receptors and a defective post-receptor step." (PMID 31752481, 2020). "We investigated insulin and insulin resistance because they are risk factors for cardiovascular disease and mortality, while other study outcomes are widely accepted targets for cardiovascular preventive treatments." (PMID 32928159, 2020). "NAFLD and NASH are often associated with insulin resistance, glucotoxicity and accompanied by an increase in cholesterol, triglycerides, insulin, as well as decrease in adiponectin." (PMID 33092030, 2020). "Altogether, DKO mice displayed reduced glucose tolerance and insulin sensitivity, which are established risk factors of insulin resistance (IR) and type 2 diabetes." (PMID 32796650, 2020). "Here, we provided evidence that LNK was a regulator of the insulin signaling pathway and a major cause of impaired glucose metabolism, the defining feature of insulin resistance." (PMID 32911464, 2020). "Type 2 Diabetes mellitus (T2DM) is a progressive disease characterized by insulin resistance and a relative or absolute deficiency of insulin production." (PMID 31941993, 2020). "Delayed insulin treatment caused by patients’ psychological insulin resistance (PIR) can lead to poor glycaemic control, complications and ultimately deteriorated quality of life (Nam, Chesla, Stotts, Kroon, & Janson, 2010)." (PMID 32257276, 2020). "Regarding insulin-resistance, the associated hyperinsulinemia directly increases cardiac mass and left ventricle dysfunction, through the interaction between insulin, its receptor and insulin-like growth factor-1 (IGF-1) receptor, expressed in the myocardium." (PMID 32033349, 2020). "Insulin resistance (IR) is a deceptively complex condition characterised by impaired insulin responsiveness in target tissues, causing the β-cells in the pancreas to continue to produce extra insulin, leading to eventual malfunction through oxidative stress." (PMID 33066504, 2020). "Then lipid-induced insulin resistance in skeletal muscle occurs, which stems from deficiency in insulin-stimulated glucose transport activity." (PMID 32117054, 2020). "Our previous study showed that NSY mice under sucrose administration for 12 weeks developed markedly impaired glucose tolerance, impaired insulin secretion, and insulin resistance associated with obesity." (PMID 32703163, 2020). "There is evidence that GM3 regulates insulin signaling by lateral association with InsR, and thereby triggers development of insulin resistance." (PMID 32731387, 2020). "Similar to the other studies, our results show that BMI has a meaningful effect on insulin resistance due to the higher leptin levels in obese patients, so weight loss is considered as an important strategy in increasing insulin sensitivity." (PMID 33680012, 2020). "It is stated in recent studies that there is an association between decreased insulin sensitivity and chronic inflammation in people with obesity and insulin resistance." (PMID 32907593, 2020).
Insulin resistance (continued). "Generally, adiponectin improves insulin sensitivity, which is associated with low blood insulin and the homeostasis model assessment of insulin resistance (HOMA-IR) index." (PMID 32492866, 2020). "Oxidative stress causes the adipocytokine dysregulation and inhibition of insulin signals, thus bringing about insulin resistance." (PMID 32148647, 2020). "AAV8.Ucn2 gene transfer was associated with increased insulin sensitivity, reduced hyperglycemia and fatty liver in mice that developed insulin resistance." (PMID 31790421, 2019). "Previous evidence showed that infertile women and ART population were susceptible to develop GDM; yet, the mechanism underlying ART-induced insulin resistance and insulin requirement is partially understood." (PMID 31656196, 2019). "The two main types of the disease are type 1 diabetes (T1D) characterized by absolute deficiency of endogenous insulin production and type 2 diabetes (T2D) characterized by partial deficiency of endogenous insulin production and insulin resistance." (PMID 30774850, 2019). "It causes cell damage and insulin resistance, it disorders insulin secretion and dysregulates glucose." (PMID 30430418, 2019). "The insulin/insulin receptor substrate (IRS)/phosphatidylinositol 3‐kinase (PI3K)/protein kinase B (Akt)/GLUT4 pathway plays a crucial role in insulin resistance and is closely associated with T2DM." (PMID 31389668, 2019). "Although WFA reduces body weight in diet-induced obese mice, the peripheral effects of WFA on weight regulation and the mechanisms underlying its insulin sensitizing effect in obesity related insulin resistance are yet to be unveiled." (PMID 31226166, 2019). "Insulin resistance increases the burden placed on pancreatic ß cells to increase insulin synthesis and secretion that leads to associated defects including decreased ß cell number, chronic ER stress and/or oxidative stress, and a loss of ß cell identity." (PMID 31184304, 2019). "This feedback response would be blunted in obese patients exhibiting underlying insulin resistance and those with diabetes where the insulin secretory capacity is compromised." (PMID 31443495, 2019). "Psychological insulin resistance has been associated with poor adherence to insulin injection in insulin-treated patients (Yavuz, Ozcan, & Deyneli, 2015)." (PMID 30807441, 2019). "Excess body weight is the primary cause of MetS due to the increase in insulin production, as well as the likelihood of developing insulin resistance, a central pathophysiological factor in the development of MetS." (PMID 30864629, 2019). "Insulin is an anabolic hormone and insulin resistance is associated with accelerated muscle protein degradation." (PMID 31262307, 2019). "Insulin resistance causes target tissues to fail to respond properly to normal levels of circulating insulin, which is a common pathological condition known as type 2 diabetes mellitus (T2DM)." (PMID 30871060, 2019). "Higher serum albumin in the setting of insulin resistance is thought to be the consequence of increased albumin production caused by insulin stimulation." (PMID 30786864, 2019). "Obesity (body mass index ≥30 kg/m2) is a broadly accepted risk factor of systemic insulin resistance, and loss of skeletal muscle insulin sensitivity is the first sign of such resistance in human subjects." (PMID 31195596, 2019). "T2DM is characterized by impaired insulin secretion (i.e. insulin deficiency) and insulin sensitivity (i.e. insulin resistance), explaining the underlying pathophysiological mechanism for hyperglycemia (fasting serum blood glucose > 7 mmol/L)." (PMID 31163064, 2019). "And evidence for the coexistence of insulin resistance and insulin deficiency in childhood-onset Type 1 diabetes adults has also been demonstrated by the insulin-glucose clamp technique." (PMID 30733818, 2019).
Insulin resistance (continued). "This adipocyte expansion has been long associated with metabolic disease and insulin resistance, implicating adipocyte-size dependent regulation of insulin signalling and growth." (PMID 31112068, 2019). "AM-Ex appeared to reduce the risk factors associated with insulin resistance by controlling multiple pathways associated with insulin signaling, adipogenesis, and inflammation." (PMID 31137884, 2019). "Earlier reports showed that IL-1β is associated with defective secretion of insulin as well as the development of insulin resistance." (PMID 30937278, 2019). "Disorders in insulin signaling through disruption in lipid and glucose metabolism cause insulin resistance, an important characteristic feature of type 2 diabetes (Cordero‐Herrera, Martín, Bravo, Goya, & Ramos, 2013)." (PMID 30680172, 2019). "The agonistic reaction produces an inflammatory reaction, affects the secretion and regulation of insulin, and causes the body to produce insulin resistance, which affects the stability of blood sugar levels." (PMID 31771577, 2019). "The role of apelin in insulin resistance has also been studied in mice with generalized apelin deficiency; these mice were insulin resistant and the resistance was reversed after exogenous apelin administration." (PMID 31492821, 2019). "Among diabetic types, type 2 is the most common occurrence in adults due to a complex metabolic abnormality including insulin resistance, hyperglycemia, and deficient insulin secretion." (PMID 30700006, 2019). "Insulin and insulin resistance were also associated with higher risk of angina in men only, with a more obvious sex difference for BMI-adjusted insulin (p value for sex difference 0.04), than insulin (p value for sex difference 0.08)." (PMID 31508506, 2019). "In contrast, AAM can mitigate against insulin resistance with improved insulin sensitivity associated with increased numbers of AAM in adipose tissue." (PMID 30553769, 2019). "Insulin has a pleiotropic effect on different metabolic tissues; thus, insulin deficiency and insulin resistance have adverse effect on the homeostasis of these tissues." (PMID 31683535, 2019). "Severe burns cause insulin resistance and hyperglycemia, and insulin resistance is another molecular mechanism contributing to muscle atrophy." (PMID 31353827, 2019). "Both insulin resistance in peripheral tissues and relative deficiency in insulin secretion by β-cells are crucial for the development of T2DM." (PMID 31035653, 2019). "Insulin resistance and disruption of glucose and insulin balance during pregnancy usually causes GDM." (PMID 31915414, 2019). "Fat mobilization of adipose tissue caused by deficiency of insulin or insulin resistance also results in weight loss and increasing blood lipids." (PMID 30704063, 2019). "Preceding the development of T2DM is insulin resistance (IR), a disorder associated with suppressed or delayed responses to insulin." (PMID 30781350, 2019). "Next, increased circulatory levels of the adipokine, RETN, which modulates glucose tolerance and insulin action, have been linked to a higher incidence of insulin resistance and PCOS." (PMID 30975191, 2019). "Association of oxidative stress and mitochondrial dysfunction with inflammation is implicated in type 2 diabetes, leading to insulin resistance in muscle and adipocyte cells, as well as impaired insulin secretion by the β cells of the islets of Langerhans." (PMID 31597283, 2019). "In a related study lipid profiles were consistently associated with insulin resistance because insulin affects the metabolism of HDL plasma cholesterol and triglycerides, hence central obesity is further developed with poor glucose and lipid control." (PMID 30943932, 2019). "In men, low T causes glucose intolerance and insulin resistance, and T supplementation restored glucose tolerance and insulin sensitivity." (PMID 31447783, 2019).